FGFR3 (fibroblast growth factor receptor 3)
Diseases named in the same sentence as FGFR3 in open-access papers (continued):
Sharing a sentence is not in itself a finding about the gene and the disease.
achondroplasia (continued). "Achondroplasia is a rare genetic disorder caused by a mutation in the FGFR3 gene, leading to skeletal changes and other systemic complications that greatly impact the patient's quality of life." (PMID 37404559, 2023). "In the present study, 11 cases (Case 13–14, Case 16–18, Case 20–22, Case 24–25, Case 28) had a hotspot mutation, c.1138G>A in FGFR3, that would lead to achondroplasia (MIM_100,800)." (PMID 36923788, 2023). "Achondroplasia, caused by a pathogenic variant in the fibroblast growth factor receptor 3 gene, is the most common skeletal dysplasia." (PMID 36922864, 2023). "Of the 11 de novo variants, variants in FGFR3 genes associated with achondroplasia were identified in three cases." (PMID 36797717, 2023). "Achondroplasia is due to activating mutations in the Fibroblast Growth Factor Receptor 3 gene (FGFR3), consisting in a glycine-to-arginine substitution in the transmembrane domain of the receptor (position 380) in more than 97% of cases." (PMID 37072824, 2023). "Because of this, ddPCR was applied to NIPD for the detection of paternal or de novo disease-causing mutations including achondroplasia (FGFR3) and neonatal diabetes (KCNJ11)." (PMID 37113995, 2023). "FGFR3 is a pathogenic gene that causes for achondroplasia with shortened long bones and over 80% of cases have been found with spontaneous gene mutations." (PMID 37880672, 2023). "Variants in the FGFR3 gene at different locations result in varying degrees of skeletal deformities, including thanatophoric dysplasia, achondroplasia, and hypochondroplasia (ordered by severity)." (PMID 37076826, 2023). "Transgenic mice overexpressing Fgf9 show short limbs due to reduced chondrocyte proliferation similar to bone phenotypes caused by activated FGFR3 as seen in achondroplasia." (PMID 37796615, 2023). "One of the first studies to use CNP as a potential treatment for skeletal dysplasia was done in a mouse model of achondroplasia, the most common form of dwarfism caused by mutations in the fibroblast growth factor receptor 3 (FGFR3) gene." (PMID 37373036, 2023). "98% of achondroplasia patients are caused by the variants of p.Gly380Arg in FGFR3, while the remaining 1% is attributed to other variants." (PMID 37076826, 2023). "Given that activation of FGFR3 was associated with most common achondroplasia in humans, we examined the expression of FGFR3 in the growth plate of XylT-I/KO and wild-type embryos at E18.5." (PMID 37296099, 2023). "Achondroplasia is a congenital skeletal system malformation caused by missense variant of FGFR3 gene with an incidence of 1 per 20,000–30,000 newborns, which is an autosomal dominant inheritance disease." (PMID 37076826, 2023). "People with a COL1A and COL1A2 genes mutation are more likely to develop a herniated disc, and an FGFR3 gene mutation rs28931614 (G > A, C) at position 4p:1804392 contributes to 100 percent development of achondroplasia." (PMID 36362274, 2022). "After adjusting for confounders, they found major associations between age and the frequencies of sperm with DFI and FGFR3 mutations associated with achondroplasia." (PMID 36322295, 2022). "The phenotype observed in achondroplasia results from severe disorders caused by abnormal FGFR3 activity." (PMID 36362274, 2022). "Achondroplasia is caused by a recurrent autosomal dominant gain-of-function pathogenic variant in the fibroblast growth factor receptor 3 gene (FGFR3), resulting in impaired endochondral ossification." (PMID 35698202, 2022). "Children with achondroplasia have fibroblast growth factor receptor 3 (FGFR3) mutations resulting in constitutive activity of the FGFR3 receptor, resulting in impaired chondrocyte activity and reduced bone growth." (PMID 36304528, 2022). "Since the identification of the FGFR3 gene as the causal gene for achondroplasia, the diagnosis can be easily confirmed by genetic analysis, either postnatally or prenatally." (PMID 35897040, 2022).
achondroplasia (continued). "There is no gender or ethnic disposition, and approximately 75–80% of individuals with achondroplasia are born to average-stature parents, indicating a new mutation in the FGFR3 gene in these individuals." (PMID 35897040, 2022). "Achondroplasia is an autosomal dominant disorder, caused by a recurrent pathogenic variant in the fibroblast growth factor receptor 3 (FGFR3) gene." (PMID 35897040, 2022). "All people with a single copy of the mutated FGFR3 gene have achondroplasia since this mutation has 100% dominance." (PMID 36362274, 2022). "In nearly 80% of patients, achondroplasia arises as a de novo disease-causing variant Gly380Arg in FGFR3 gene." (PMID 35986266, 2022). "Activating mutations of FGFR3 are associated with skeletal diseases like achondroplasia, hypochondroplasia, or thanatophoric dysplasia." (PMID 35682595, 2022). "Activating mutations of FGFR3 lead to a wide range of phenotypes, such as thanatophoric dysplasia, achondroplasia and hypochondroplasia, related to a different mutation site." (PMID 35949366, 2022). "Nevertheless, despite different mutation sites, only a change in the FGFR3 gene is associated with the development of achondroplasia." (PMID 36362274, 2022). "Achondroplasia is caused by a mutation in fibroblast growth factor receptor 3 (FGFR3) gene and inherited as an autosomal dominant trait." (PMID 36322295, 2022). "Achondroplasia results from a mutation in the FGFR3 gene encoding one member of the FGFR subfamily with tyrosine kinase activity." (PMID 36362274, 2022). "Endochondral ossification is responsible for bone elongation; therefore, mutations in the FGFR3 are responsible for the short limbs noted in patients with achondroplasia." (PMID 36304528, 2022). "Activating mutations in FGFR3 cause thanatophoric dysplasia, achondroplasia, and hypochondroplasia, but, recently, alterations in the FGFR3 gene have been associated with proportionate short stature." (PMID 36611397, 2022). "FGFR3 is known to cause achondroplasia with rhizomelic shortening of the limbs, characteristic facies, exaggerated lumbar lordosis, a limitation of elbow extension, genu varum, and trident hand." (PMID 35518361, 2022). "The disease is inherited in an autosomal dominant manner and is characterized by full penetration, which means that every patient with a copy of the mutated FGFR3 gene will exhibit phenotypic characteristics of achondroplasia." (PMID 34070375, 2021). "Achondroplasia is the most common type of skeletal dysplasia, caused by a recurrent pathogenic variant in the fibroblast growth factor receptor 3 (FGFR3)." (PMID 34332609, 2021). "The common findings of macrocephaly and facial anomalies accompany dwarfism in these patients.Fibroblast growth factor receptor 3(FGFR3) gene mutations are common causes of achondroplasia." (PMID 34430961, 2021). "Two examples of FGFR3 mutations illustrate the use of these charts; a girl with achondroplasia (in blue) and one with hypochondroplasia (in green)." (PMID 33220165, 2021). "The gold standard for achondroplasia diagnosis remains the genetic examination of the amniotic fluid and identification of a mutation in FGFR3, which is located on the short arm of chromosome 4." (PMID 34070375, 2021). "Gain-of-function mutations in both human and mice FGFR3 result in achondroplasia characterized by a short limb phenotype, while knockout of FGFR3 in mice produces a long limb phenotype." (PMID 35047496, 2021). "Several studies pointed towards a cross-talk of FGFR3 signaling with the cilia-associated Hh pathway that was found inhibited in mouse models of achondroplasia, due to the defective ciliogenesis." (PMID 34207779, 2021). "The most common and specific FGFR3 mutation in achondroplasia is c.1138G>A or c.1620G>C (p.G380R) and in hypochondroplasia is c.1620C>A or c.1620C>G (p.N540K)." (PMID 34740356, 2021).
achondroplasia (continued). "Possible additive effect from presence of FGFR3 mutation and an additional syndromic condition is shown in a boy with achondroplasia and Down syndrome and a combination of achondroplasia and Kabuki syndrome in a girl." (PMID 33220165, 2021). "Definitive prenatal diagnosis can be offered at present only for achondroplasia gene (FGFR3) mutation, the empiric recurrence risk being around 5% (to account for possibility of germinal mosaicism)." (PMID 33854687, 2021). "Simultaneously, a dwarf phenotype similar to human achondroplasia, usually caused by activating mutations in FGFR3, was also observed in the SPRED2 knockout mice." (PMID 34071546, 2021). "Among the 208 infants in this study with a known family medical history, a de novo mutation in the FGFR3 gene was the cause of achondroplasia in 166 cases (79.8%), and family-related prevalence of the disease was confirmed in only 42 (20.2%) cases." (PMID 34070375, 2021). "Achondroplasia is the most common form of disporportionate short stature in humans, caused by a common pathogenic variant in the fibroblast growth factor receptor 3 gene that confers a gain of function." (PMID 34341520, 2021). "FGFR3 is associated with multiple skeletal dysplasias including thanatophoric dysplasia, achondroplasia, and Crouzon syndrome and hypochondroplasia." (PMID 34194850, 2021). "The mutation in fibroblast growth factor receptor 3 (FGFR3) gene responsible for rhizomelic short stature was present in infant producing clinical picture of achondroplasia, which is autosomal dominant genetic condition." (PMID 33854687, 2021). "Another effect of the FGFR3 mutation and delayed ossification that affects the facial appearance and wellbeing of patients with achondroplasia is hypoplasia and the abnormal tissue formation of the mandible." (PMID 34070375, 2021). "Achondroplasia is the most common form of short limb dwarfism due to a mutation in the FGFR3 gene, with a prevalence of 1 in 25,000 individuals." (PMID 33889553, 2021). "Achondroplasia is caused by pathogenic variants in the fibroblast growth factor receptor 3 gene that lead to impaired endochondral ossification." (PMID 34341520, 2021). "In a similar way, several mutations that cause excessive activation of FGFR3 can cause achondroplasia in humans." (PMID 35047584, 2021). "Gain-of-function missense mutations in FGFR3 produce human skeletal dysplasias, including achondroplasia and thanatophoric dysplasia, and frequently occur in cancer." (PMID 34207779, 2021). "Within the PAC, 76.0% had a de novo FGFR3 pathologic variant and 1,094 (79.6%) had one or more achondroplasia-related surgeries." (PMID 34006999, 2021). "Activated FGFR germline mutations can lead to skeletal disorders, such as a mutation in FGFR3 which can lead to growth defects and human dwarfism achondroplasia (ACH)." (PMID 34830836, 2021). "Activation mutations of fibroblast growth factor receptor 3 (FGFR3) in human cause chondrodysplasia including achondroplasia, hypochondroplasia as well as thanatophoric dysplasia through inhibiting chondrocyte proliferation and differentiation." (PMID 34282140, 2021). "Injecting soluble sFGFR3 into mice harboring tumors with FGFR3 activating mutations neutralized FGFR ligands (FGF2, FGF9, FGF18, etc.)and rescued the symptoms of FGFR3 germline mutation, which causes achondroplasia of mice after birth." (PMID 34638374, 2021). "Editor's choice: In a mouse model of achondroplasia, targeting an Fgfr3-activating mutation to immature osteoblasts led to osteopenia and induced craniofacial membranous bone defects." (PMID 33737326, 2021). "FGFR3 mutations have been reported to cause various types of skeletal dysplasia, especially achondroplasia and hypochondroplasia, in an autosomal-dominant manner." (PMID 34740356, 2021).
achondroplasia (continued). "Examples include achondroplasia, hypochondroplasia, lacrimo-auriculo-dento-digital syndrome, and thanatophoric dysplasiam, each of which is attributed to germline FGFR3 mutations that result in their varied phenotypes." (PMID 32066498, 2020). "Autosomal dominant mutations in fibroblast growth factor receptor 3 cause achondroplasia, the most common form of dwarfism in humans." (PMID 32335626, 2020). "Achondroplasia is caused by a mutation in the fibroblast growth factor receptor-3 gene (FGFR3), which is located at 4p16.3." (PMID 32335626, 2020). "Achondroplasia is caused by gain-of-function mutations in FGFR3 gene and leads to short-limb dwarfism." (PMID 33262386, 2020). "In the early 90’s, different mutant alleles in FGFR3 were discovered that are causal for achondroplasia." (PMID 33370388, 2020). "Accordingly, we focused on a mouse model with a dominant point mutation in Fgfr3 (Fgfr3 Gly369Cys mutation), causing dwarfism with features mimicking human achondroplasia; further, homozygous mutant mice have more severe effects than heterozygotes." (PMID 32929070, 2020). "Mutations in FGFR3 on chromosome 4p16.3 were first described as the cause of achondroplasia in 1994." (PMID 32144686, 2020). "Achondroplasia is caused by a heterozygous, activating mutation in the fibroblast growth factor receptor‐3 (FGFR3) gene at position 1138." (PMID 32144686, 2020). "It is comprised of the extracellular domain of the FGFR3 and it is believed to act as a decoy receptor normalizing the aberrant signaling of the mutated human FGFR3 in achondroplasia." (PMID 33370388, 2020). "This is particularly salient for monogenic disorders; for example, over 80% of achondroplasia cases occur from recurrent de novo mutations in FGFR3." (PMID 32519380, 2020). "Achondroplasia is a rare genetic disorder caused by mutations in the Fibroblast Growth Factor receptor 3 (FGFR3)." (PMID 33370388, 2020). "Achondroplasia (ACH) is a common skeletal dysplasia with shorten-limbed short stature caused by gain-of-function mutation in fibroblast growth factor receptor 3 (FGFR3) gene." (PMID 32875008, 2020). "Achondroplasia is a genetic disease which causes short stature due to a gain-of-function mutation in fibroblast growth factor receptor 3 (FGFR3)." (PMID 33002060, 2020). "Achondroplasia was molecularly confirmed in all participants, all had the most commonly reported c.1138G > A (p.Gly380Arg) mutation in the FGFR3-gene." (PMID 32450891, 2020). "In contrary, targeted overexpression of FGFR3 bearing the achondroplasia mutation to cartilage of transgenic mice produced a small mouse with short bones resembling those seen in human achondroplasia." (PMID 33370388, 2020). "For example, activating FGFR3 mutations associated with achondroplasia lead to structural anomalies of MC and condylar cartilages of the mandible, resulting in mandibular hypoplasia and dysmorphogenesis." (PMID 31064775, 2019). "Because nearly all instances of achondroplasia arise from a change in the same base pair of FGFR3, targeted mutation analysis is the routinely employed molecular test." (PMID 30606190, 2019). "In these, and in achondroplasia, FGFR3 mutations cause abnormalities of ossification in membranous bone including premature sutural fusion." (PMID 30606190, 2019). "Third, even outside of the cancer setting, different tissues can have opposite functions for the same signaling pathway; FGFR3 activating mutations stimulate spermatocyte cell division but inhibit chondrocyte cell division, leading to achondroplasia." (PMID 30962767, 2019). "Rapidly it was demonstrated that nearly all instances of achondroplasia are caused by FGFR3 mutations." (PMID 30606190, 2019). "The cause of achondroplasia was identified to be a gain-of-function mutations in the gene for the fibroblast growth factor receptor 3 (FGFR-3) and is known to be an autosomal dominant trait." (PMID 31399110, 2019).
achondroplasia (continued). "Mechanistically, achondroplasia is an autosomal dominant disease caused by a mutation in the fibroblast growth factor receptor 3 (FGFR3) gene that corresponds to a Gly380Arg substitution in 90% of the cases." (PMID 31727132, 2019). "Given that the activating mutation of FGFR3 that results in achondroplasia causes a general inhibition of endochondral bone growth, of course one would anticipate that all of the long bones of the body will grow slowly; and they do." (PMID 30606190, 2019). "For instance, transgenic FGF-2 overexpression results in dwarfism in mice, and activating FGFR3 mutations lead to achondroplasia and shortened long bones with disorganized chondrocyte columns in growth plate." (PMID 31371388, 2019). "Fibroblast growth factor receptor 3 gene (FGFR3) mutations lead to group of autosomal dominant disorders that in descending severity include; Thanatotrophic dysplasia (TD), Achondroplasia (ACH) and Hypochondroplasia (HCH)." (PMID 31888683, 2019). "Previous studies have confirmed the pathogenicity of these variants in skeletal dysplasia, and c.1138G>A is the most common FGFR3 mutation underlying achondroplasia; (Foldynova‐Trantirkova, Wilcox, & Krejci, 2012)." (PMID 31566912, 2019). "We have recently successfully developed a recombinant protein treatment, using a decoy soluble FGFR3 (sFGFR3), restoring full bone growth in mice carrying the achondroplasia mutation (Fgfr3ach/+) opening the way of potential treatment in humans." (PMID 29652901, 2018). "Achondroplasia is caused by mutations in the fibroblast growth factor receptor 3 (FGFR3) gene which results in over-activation of the receptor, interfering with normal skeletal development leading to disproportional short stature." (PMID 29323153, 2018). "Activating mutations of FGFR3, which have an effect on the negative regulation of cartilage growth are encountered in hypochondroplasia and achondroplasia." (PMID 29739731, 2018). "Among the chondrodysplasias occurring due to gain-of-function mutations in FGFR3 gene, achondroplasia is the most common dwarfism." (PMID 30381765, 2018). "Molecular analysis of Achondroplasia in Nepalese cases has given a similar scenario of sporadic occurrence of ACH due to mutation at 1138th nucleotide of FGFR3 gene found worldwide." (PMID 30381765, 2018). "In previous studies of thanatophoric dysplasia and achondroplasia mouse models carrying activating FGFR3 mutations, BMN 111 was shown to improve the endochondral development of the growth plate and subsequent growth of long bones." (PMID 30048539, 2018). "Achondroplasia is caused by a single point gain-of-function mutation in the gene coding for fibroblast growth factor receptor 3 (FGFR3)." (PMID 28224446, 2017). "Achondroplasia is caused by a mutation in fibroblast growth factor receptor 3 (FGFR3), which normally has a negative regulatory effect on bone growth." (PMID 28937639, 2017). "Achondroplasia is caused by a mutation in the FGFR3 gene resulting in abnormal endochondral ossification." (PMID 28224446, 2017). "In achondroplasia, the G380R mutation, located in the transmembrane domain of FGFR3, extends the signaling cascade resulting in prolonged bone growth inhibition." (PMID 28224446, 2017). "Another essential regulator of bone elongation is FGF receptor 3 (FGFR3); activating mutations of FGFR3 inhibit bone growth, causing achondroplasia, in which human height is reduced by ~25%." (PMID 29199951, 2017). "In fact, the most common de novo mutated codon associated with human disease is a GGG>AGG or CGG mutation in codon 380 of FGFR3 gene which results in achondroplasia." (PMID 26910043, 2016). "The de novo mutation detected in the plasma sample, namely, c.1138G>A (p.G380R) in FGFR3 (NM_000142.4), is the major pathogenic variant known to cause achondroplasia, which corresponds to 98% of achondroplasia." (PMID 27433940, 2016).